AHR (aryl hydrocarbon receptor)
Diseases named in the same sentence as AHR in open-access papers (continued):
Sharing a sentence is not in itself a finding about the gene and the disease.
folate deficiency (1 paper, 2012). A nutritional condition produced by a deficiency of FOLIC ACID in the diet. "Precise biological mechanisms of exposure to Dioxin are epigenetic, based on activation of the AhR/ARNT (aryl hydrocarbon receptor/aryl hydrocarbon receptor nuclear translocator) complex of spermatogenesis, leading to folate deficiency as the cause of NTD phenotype." (PMID 22900183, 2012).
folliculitis (1 paper, 2022). Inflammation of the hair follicles. "Besides concerns on phase 1 metabolism by CYP1A1 due to AHR activation, a specific side effect, folliculitis, is reported in patients treated with topical AHR-activating therapies, such as coal tar and tapinarof." (PMID 35163694, 2022).
gallstones (1 paper, 2025). Solid crystalline precipitates in the biliary tract, usually formed in the gallbladder, resulting in the condition of cholelithiasis. "For instance, tryptophan metabolites regulate bile acid synthesis via the aryl hydrocarbon receptor (AHR) signaling pathway, while sphingolipid metabolites participate in gallstone formation by modulating the expression of cholesterol transport proteins." (PMID 40636353, 2025).
gingivitis (1 paper, 2023). A disorder involving inflammation of the gums; may affect surrounding and supporting structures of the teeth. "Conversely, S. mitis also has beneficial functions, as it can produce antimicrobials that inhibit the growth of human gingivitis pathogens, and its lysate can activate the aryl hydrocarbon receptor (AhR) of oral epithelial cells, leading to wound healing." (PMID 37014220, 2023).
glucose transport disorder (1 paper, 2024). An inherited metabolic disease that is has its basis in the disruption of glucose transport. "Collectively, these data suggest that the activation of AhR-mediated signaling contributes to BPA-induced glucose transport disorder in ovarian granular cells." (PMID 38200540, 2024).
Granuloma (1 paper, 2012). A compact, organized collection of mature mononuclear phagocytes, which may be but is not necessarily accompanied by accessory features such as necrosis. "Subcutaneous nodules are granulomas, dominated by monocyte/macrophages but our data suggest that the difference in AHR gene expression is not entirely due to this difference in inflammatory cell type." (PMID 23036591, 2012).
hair diseases (1 paper, 2025). "The role of the AhR pathway in hair diseases remains poorly understood." (PMID 40162433, 2025).
Hearing impairment (1 paper, 2020). A decreased magnitude of the sensory perception of sound. "PFASs are known ligands of the AhR and thus might induce hearing impairment through this pathway." (PMID 32806617, 2020).
hematoma (1 paper, 2025). A hematoma is a collection of blood from a vascular structure into an extravascular space. "In support of important role of AhR in microglia in ICH, the selective AhR-deficiency in MG in mice worsened the hematoma clearance and impaired post-ICH recovery and weakened ITE from mediating therapeutic effect." (PMID 40963261, 2025). "Encouraged by the in vitro data suggesting a stimulating role of AhR on the MG-mediated erythrophagocytosis, a process that could help in hematoma cleanup and recovery after ICH, we tested if the selective activator of AhR, ITE, improves post-ICH recovery." (PMID 40963261, 2025). "Also, we established that the AhR agonists used as treatment for ICH in mice improve hematoma resolution and neurological recovery after ICH and that the selective AhR deficiency in MG worsens the hematoma clearance process and impairs post-ICH recovery." (PMID 40963261, 2025). "Our ultimate goal was to probe if AhR, that is, abundant in MG acts as a regulator of phagocytic function to benefit post-ICH hematoma clearance and functional recovery." (PMID 40963261, 2025). "Using mouse ICH model, we established that AhR is abundant in MMΦ located near hematoma, and that AhR agonists, ITE, used as treatment for ICH, improved both hematoma clearance and neurological recovery." (PMID 40963261, 2025).
hemorrhage (1 paper, 2005). Loss of blood from the vascular compartment to the exterior or into nonvascular body space as a result of rupture or severance of the blood vessels. "Intracranial hemorrhage was still present among most embryos that had circulation and a lack of CYP1A immunofluorescence (data not shown), which strongly suggests that the underlying pathophysiology is AhR independent." (PMID 16330359, 2005).
Holt-Oram syndrome (1 paper, 2012). Holt-Oram syndrome (HOS) is the most common form of heart-hand syndrome and is characterized by skeletal abnormalities of the upper limbs and mild-to-severe congenital cardiac defects. "The minor allele is predicted to bind TBX5 and AhR; the former has been linked to a number of cardiac phenotypes including Holt-Oram syndrome and atrioventricular conduction and the latter regulates cardiac size, a known risk factor for QT-prolongation and cardiac sudden death." (PMID 22912591, 2012).
hyperuricemia (1 paper, 2022). An abnormally high level of uric acid. "Fisetin, a bioactive flavonol, was reported to improve hyperuricemia-induced CKD via regulating gut microbiota-mediated tryptophan metabolism and AHR activation." (PMID 35865941, 2022).
Hypervolemia (1 paper, 2024). An increase in the amount of intravascular fluid, particularly in the volume of the circulating blood. "However, as this effect is only very small, we do not believe that AhR plays a major role in IL-10 signaling in hypervolemia." (PMID 38612530, 2024).
Hypoglycemia (1 paper, 2016). A decreased concentration of glucose in the blood. "Hence, it seems that the AhR−/− mice is likely at a metabolic advantage through enhanced gluconeogenesis in liver during fasting to regulate hypoglycemia." (PMID 28721249, 2016).
hypothyroidism (1 paper, 2019). Abnormally low levels of thyroid hormone. "Third, this study revealed that COP subjects who received HBOT also had a higher risk for hypothyroidism, with an AHR similar to the overall COP cohort in comparison with the non-COP cohort." (PMID 31712674, 2019).
Idiopathic Infantile Nystagmus (1 paper, 2020). "We recently described a consanguineous Israeli Arab family with three children affected by Idiopathic Infantile Nystagmus (IIN) and foveal hypoplasia, due to a homozygous stop mutation c.1861C > T; p.Q621∗ in the gene encoding the aryl hydrocarbon receptor (AHR; MIM 600253)." (PMID 33193710, 2020).
intestinal motility disorders (1 paper, 2025). "Research indicates that pharmacological or dietary regulation of AHR activity in enteric neurons can alleviate intestinal motility disorders." (PMID 39973939, 2025).
intracerebral hemorrhage (1 paper, 2021). A cerebrovascular disorder characterized by bleeding into one or both cerebral hemispheres including the basal ganglia and the cerebral cortex. "The latest data showed that intracerebral hemorrhage in mouse induced the expression of AhR in microglia and neutrophils." (PMID 34830207, 2021).
intracranial hemorrhage (1 paper, 2005). Bleeding within the SKULL, including hemorrhages in the brain and the three membranes of MENINGES. "Because cardiac output and intracranial hemorrhage are likely to be functionally related, it was difficult to determine whether AhR activation or CYP1A induction played a causal role in intracranial hemorrhage." (PMID 16330359, 2005). "Weathered crude oil also produced additional defects in zebrafish embryos (intracranial hemorrhage and finfold defects) that either are not observed with exposure to individual model PAHs or dioxins, or arise during an earlier developmental stage than AhR-mediated TCDD toxicity." (PMID 16330359, 2005).
intracranial meningioma (1 paper, 2023). A meningioma that arises within the cranial cavity. "Relatively recently, AhR expression was detected in human brain meningiomas." (PMID 37305351, 2023).
intrahepatic cholestasis (1 paper, 2020). A cholestasis characterized by impairment of the bile flow caused by obstruction located in the liver. "Furthermore, a lipidomic study of ANIT-induced intrahepatic cholestasis uncovered the role of the aryl hydrocarbon receptor (AHR) in regulating expression of choline kinase (CHK) in mice." (PMID 32012846, 2020).
ischemic cardiomyopathy (1 paper, 2023). Ischemic cardiomyopathy is a cardiomyopathy in which a weakness in the muscle of the heart due to inadequate oxygen delivery to the myocardium with coronary artery disease being the most common cause. "Therefore, higher AhR expression might not only increase atherosclerotic risk but also facilitate EAT to release cytokines and fatty acids, causing adverse myocardial remodeling in ischemic cardiomyopathy." (PMID 37749614, 2023).
Jaundice (1 paper, 2014). Yellow pigmentation of the skin due to bilirubin, which in turn is the result of increased bilirubin concentration in the bloodstream. "The induction of AhR in the liver by those ligands induces upregulation of Ugt1a1 to prevent jaundice in neonates and to regulate antioxidant AhR effects in the adult liver." (PMID 25566253, 2014).
joint disorders (1 paper, 2021). "Although the pathogenic role of AHR activation in joint disorders is not fully understood, TCDD-mediated AHR activation induces the apoptosis of chondrocytes via ROS generation." (PMID 33445793, 2021).
leishmaniasis (1 paper, 2019). Infectious disease that is transmitted through the bite of hematophagous female phlebotomine sand flies. "Therefore, and because AhR has recently been identified as an important regulator of innate immunity and was implicated in regulation of resistance to experimental leishmaniasis, we focused on AhR." (PMID 31749794, 2019). "Since increased L. major-induced gene-expression in C57BL/6 mice in comparison to BALB/c mice is associated with resistance and AhR-induced TNF is one known decisive agent in leishmaniasis, we wondered if susceptible mice could benefit from local AhR activation during early leishmaniasis." (PMID 31749794, 2019). "Since effects of TCDD were also seen in SCID mice, this argues for T-cell independent effects of AhR-signaling in experimental leishmaniasis." (PMID 31749794, 2019). "Our results demonstrate that local activation of AhR has a beneficial effect in experimental leishmaniasis." (PMID 31749794, 2019). "Our data newly establish that the local signaling by AhR increases resistance early during experimental leishmaniasis." (PMID 31749794, 2019). "It was also recently described as a regulator in macrophage polarization and several publications have reported a role for AhR in resistance to experimental Leishmaniasis." (PMID 31749794, 2019). "Importantly, while TNF is induced in LPS-stimulated Ahr knockout macrophages, production of NO is inhibited, indicating an ambiguous nature of AhR-signaling in terms of macrophage functions relevant for Leishmaniasis." (PMID 31749794, 2019). "There are also some data on the relevance of AhR for experimental leishmaniasis." (PMID 31749794, 2019).
lupus nephritis (1 paper, 2019). Glomerulonephritis in the context of systemic lupus erythematosus. "Adjunctive therapy with laquinimod, an aryl hydrocarbon receptor (AhR) agonist, is under evaluation in ongoing phase II clinical trials in SLE patients with active lupus nephritis." (PMID 31640263, 2019).
macrosomia (1 paper, 2022). "The median level of serum AhR-TEQ in the pregnant women giving birth to infants with normal BW were slightly lower than those with low BW (<2500 g) or macrosomia infants (BW > 4500 g)." (PMID 35051068, 2022).
melasma (1 paper, 2025). "Synergistically with sun exposure and genetic factors, it may be a risk factor for the onset and maintenance of melasma pigmentation, due to the cutaneous penetration of PAHs and activation of AhR." (PMID 40812224, 2025). "In conclusion, greater expression of AhR was observed in the epidermis and pilosebaceous units of melasma skin compared to adjacent skin, suggesting a role in its pathogenesis." (PMID 40812224, 2025). "The higher expression of AhR in the epidermis and pilosebaceous units in melasma may indicate the involvement of environmental stimuli (especially pollution) in its pathogenesis and contribute to the higher prevalence of melasma in urban centers." (PMID 40812224, 2025). "Since, to date, no study has evaluated the role of AhR in melasma, an investigation was conducted to compare its differential activation in melasma and adjacent healthy skin." (PMID 40812224, 2025).
mental disorder (1 paper, 2019). A disease that has its basis in the disruption of mental process. "In the subjects without mental disorder, the AHR was 3.2 (95% CI: 2.5−4.1)." (PMID 31712674, 2019).
Miscarriage (1 paper, 2024). A pregnancy that ends at a stage in which the fetus is incapable of surviving on its own, defined as the spontaneous loss of a fetus before the 22th week of pregnancy. "AhR/lnc‐HZ10/BRCA1 axis can be considered as a promising target for alleviation of unexplained miscarriage." (PMID 38286681, 2024). "Based on these observations, we suggested that the AhR/lnc‐HZ10/BRCA1 axis might be considered as a promising target for treatment against unexplained miscarriage." (PMID 38286681, 2024). "Therefore, it is suggested that AhR/lnc‐HZ10/BRCA1 axis may be a promising target for alleviation of unexplained miscarriage." (PMID 38286681, 2024). "Thus, BPDE exposure triggered this AhR/lnc‐HZ10 feedback loop, which subsequently suppressed HR repair and possibly induced miscarriage." (PMID 38286681, 2024).
muscle atrophy (1 paper, 2025). The loss of muscle tissue due to inactivity or disease. "Excessive colonic Kyn is released into circulation, transported into skeletal muscle cells, and binds to the aryl hydrocarbon receptor (AHR), consequently triggering AHR nuclear translocation and initiating the transcription of skeletal muscle atrophy-related genes." (PMID 39950940, 2025).
muscular atrophy (1 paper, 2021). "Both toxins play an important role in inducing muscular atrophy through various mechanisms (e.g., pro-inflammatory cytokines release or activation of some pathways, such as aryl hydrocarbon receptor (AhR), NFκB and SRAA)." (PMID 34357944, 2021).
Myelodysplasia (1 paper, 2015). Clonal hematopoietic stem cell disorders characterized by dysplasia (ineffective production) in one or more hematopoietic cell lineages, leading to anemia and cytopenia. "We sought to determine gene changes related to alterations in HSC function and the myelodysplasia elicited by AhR loss in aging mice." (PMID 26208102, 2015). "Aging AhR-KO mice develop a myelodysplasia and HSCs exhibit premature exhaustion and decreased self-renewal capacity." (PMID 26208102, 2015). "The goal of the current study was to gain insight into cellular and molecular mechanisms of AhR in HSC aging, and, in particular, AhR-regulated pathways contributing to the altered self-renewal and myelodysplasia observed in aging AhR-KO mice." (PMID 26208102, 2015). "However, the exact AhR-regulated pathways that control HSC proliferation-balance and development of premature HSC exhaustion and myelodysplasia in AHR-KO mice remain unclear." (PMID 26208102, 2015).
nasal polyp (1 paper, 2025). "This study aims to investigate how PM2.5 stimulates human nasal mucosal epithelial cells, activates IL4I1, modulates AhR expression, and induces nasal mucosal damage and tissue remodeling, thereby contributing to nasal polyp formation." (PMID 40559961, 2025). "We elucidated how PM2.5 stimulates human nasal mucosal epithelial, activate IL4I1, modulates AhR expression, and induces nasal mucosal damage and tissue remodeling, ultimately contributing to nasal polyp formation." (PMID 40559961, 2025).
neck tumor (1 paper, 2018). "Antagonism or selective activation of AHR has been demonstrated to suppress TPA-induced ear edema in mice, repress inflammatory signaling in primary human fibroblast-like synoviocytes, murine peritoneal macrophages, human head and neck tumor cells." (PMID 30501068, 2018).
Neurodegeneration (1 paper, 2023). Progressive loss of neural cells and tissue. "However, it remains unclear as to how modulation of AhR expression by thrombin is related to the development of neurodegeneration disorders." (PMID 37511175, 2023).
neurodevelopmental disabilities (1 paper, 2009). "Consequently, the AhR-AHRE-III-mediated pathway participates in neural development rather than xenobiotic metabolism or the detoxification process, and TCDD may induce neurodevelopmental disabilities through the AhR-AHRE-III-mediated pathway." (PMID 19500377, 2009).
neurofibromatosis 1 (1 paper, 2021). "The AHR-activating antimalarial drugs are potentially applicable for treating the devastating cutaneous neurofibromas in neurofibromatosis." (PMID 34011935, 2021). "The antimalarial drugs HCQ, CQ are feasible options to restore the MMP1 production and release in stromal cells in neurofibromatosis 1 by dual mechanisms, one by activating the AHR-ERK-MMP1 pathway and the other by inhibiting the lysosomal degradation of MMP1 proteins." (PMID 34011935, 2021).
nicotine dependence (1 paper, 2025). Physical and psychological dependence on nicotine. "Previous reports indicated that SLC2A13, BHLHE41, VGF and AHR variants are associated with heavy and problem drinking in patients as well as with nicotine dependence in tobacco users." (PMID 39880903, 2025).
non-melanoma skin carcinoma (1 paper, 2016). "This inhibition allows ultraviolet-induced DNA damage and reactive oxygen species to accumulate within keratinocytes; hence, overexpression of AHR may contribute to the development of non-melanoma skin cancers." (PMID 27424798, 2016).
ocular infection (1 paper, 2018). "Therefore, AHR is required for the response to at least one viral pathogen and a non-toxic AHR agonist may have the capability to treat an ocular infection from the herpes simplex virus." (PMID 30513921, 2018).
Opportunistic infection (1 paper, 2025). An infection that is caused by a pathogen that would generally not be able to cause an infection in a host with a normal immune system. "Furthermore, these data suggest that IDO1 or AHR are potential host targets for the prevention of opportunistic infections in patients undergoing antimicrobial therapy." (PMID 40387573, 2025).
otitis media (1 paper, 2021). Inflammation of the anatomical structures of the middle ear, which is most often caused by an infectious process. "Given that children exhibited increased incidences of otitis media following exposure to PCBs and dioxins, it is tempting to speculate that this increase was due, in part, to AHR activation and consequently decreased nIgM producing ILB." (PMID 33936048, 2021).
Ovarian cyst (1 paper, 2024). The presence of one or more cysts of the ovary. "There was a greater expression of AHR mRNA and a lower expression of ARNT mRNA in endometriotic ovarian cysts compared with healthy ovarian tissues." (PMID 38468402, 2024).